IL10 (interleukin 10)
Diseases named in the same sentence as IL10 in open-access papers (continued):
Sharing a sentence is not in itself a finding about the gene and the disease.
asthma (continued). "Significant changes of IL-4, IL-10, and IFN-γ were observed in the asthma group in comparison to the normal group (P < 0.01, P < 0.05, and P < 0.01)." (PMID 24523826, 2014). "Interestingly, vitamin D may protect from developing respiratory infections that could serve as trigger for a deterioration of asthma and is potentially capable of overcoming the poor glucocorticoid responsiveness in severe asthmatics by upregulation of IL-10 production from CD4+ T cells." (PMID 25061262, 2014). "Thus decreased production of IL-10 in asthma might in turn lead to changes in HLA-G expression." (PMID 23327606, 2013). "Defects in IL-10 production upon CD46 activation have been demonstrated in patients with MS, asthma and rheumatoid arthritis." (PMID 23144765, 2012). "Compared with the control group, the CVA and classic asthma groups were found to have higher baseline levels of IL-5 and percentage of EOS in addition to lower concentrations of IL-10 in induced sputum." (PMID 22927709, 2012). "IL-10 values significantly increased in the CVA group after ICS treatment for 6 months, whereas levels in the classic asthma group increased after treatment for 12 months." (PMID 22927709, 2012). "Percentage proportions of CD4+ T cell staining positively for IL-2, IL-4, IL-10, IL-13, IFN-γ, and TNF-α in unstimulated whole blood were similar in children with asthma compared to healthy controls." (PMID 21197090, 2010). "In this study we used CpG/Ch.a for immunotherapy of Ch.a-induced asthma and compared the intranasal (I.N) and S.C routes of administration concerning IFN-γ, IL-10 and total IgE responses." (PMID 18799001, 2008). "However, recent studies have revealed that B cell‐derived IL‐10 exhibits an allergenic effect, while Bcl‐3 exerts a preventive role against HDM‐induced asthma by suppressing the production of IL‐10 by B cells." (PMID 41568067, 2026). "Obesity-related asthma is associated with a Th1 immune response (involving TNF-α, IFN-γ, IL-6, and IL-8) rather than a Th2 response (which involved IL-4, IL-5, IL-10, and IL-13)." (PMID 40083433, 2025). "Additionally, we explored the correlations between the microbial profiles and inflammatory cytokines known to play key roles in asthma pathogenesis, including IFN-γ, IL-4, IL-5, IL-13, IL-17A, IL-10, and TGF-β1." (PMID 40871265, 2025). "In recent years, the therapeutic potential of IL-10 in various pulmonary inflammatory diseases has attracted extensive attention, including acute lung injury (ALI), acute respiratory distress syndrome (ARDS), asthma, and pulmonary fibrosis." (PMID 41312367, 2025). "By mitigating airway hyperreactivity, reducing the levels of inflammatory cytokines (IL-4, IL-5 and IL-13) involved in the Th2 immune response, and enhancing Treg immune regulation (IL-10 and TGF-β1), hydrogen therapy has emerged as a promising adjunct strategy in asthma management." (PMID 41146240, 2025). "The interaction analysis showed that combination of both asthma and obesity had significant effects on IL-5, IL-10, IL-17A, IL-33, TNF-α, and leptin, but the effects were not synergistic or additive." (PMID 39902293, 2024). "Another study showed that curcumin, at concentrations of 50, 100, and 200 mg/kg, in comparison to dexamethasone (2 mg/kg), effectively suppressed IL-17A, improved IL-10, and inhibited both the recruitment of eosinophils and mucus overproduction in mice with OVA-induced asthma." (PMID 39263346, 2024). "Additionally, no significant variance was observed in the expression levels of IL-10 and IFN-γ between the asthma group and the control group." (PMID 38664707, 2024). "The children with asthma had an inflammatory profile that was characterized by increased levels of several pro-inflammatory cytokines, including IL-2, IL-5, IL-13, IL-17A, IL-22, IL-33, TNF-α, and reduced level of anti-inflammatory cytokine, IL-10." (PMID 39902293, 2024).
asthma (continued). "A common pathogenetic pathway is also suggested by the demonstration of the involvement of IL10 signalling in stimulating tolerance to benign allergens; IL10 pathway impairment is a well-known mechanism not only in IBD but also in allergic rhinitis and asthma development." (PMID 37111022, 2023). "In our asthma mouse model sensitized with OVA, the lung tissues were significantly damaged and the contents of inflammatory cytokines (IL-17A and IL-6) were considerably increased, while the content of IL-10 was significantly decreased." (PMID 36743692, 2023). "Further studies are needed to elucidate the mechanisms by which low IL‐10 levels protect Asian children from pediatric asthma, but this effect is not evident in Egyptians." (PMID 37937689, 2023). "Previously reported overexpressed (IL-10, MSR1, PHLDA1, SERPINB2, and CD86) and underexpressed genes (CHI3L1, CPA3, IL-8, and PI3) in severe asthma were analyzed by RT-qPCR in peripheral blood mononuclear cells (PBMCs)." (PMID 37445432, 2023). "Regarding the evaluation of inflammatory markers in the airways, we observed that the ACO group, compared to the asthma model (OVA), was higher in cells for IL-1β, IL-10, IL-17, and IFN-γ, with the exception of IL-5 positive cells that were superior in the OVA group." (PMID 37511021, 2023). "The ratio of IL-4/IL-10 levels in stunted asthmatic children tended to be higher than those in stunted children without asthma and non-stunted asthmatic children." (PMID 37760982, 2023). "The researchers found that stunted asthmatic children had higher IL-4/IL-10 ratios compared with stunted children without asthma and non-stunted children with asthma." (PMID 37760982, 2023). "As rBmTI-A reduced the concentrations of IL-5, IL-10, IL-13, and IL-17A, CrataBL reduced the numbers of IFN-γ, IL-4, IL-5, IL-13, and IL-17 positive cells in the airways and alveolar walls; both studies used an asthma model." (PMID 37511021, 2023). "Indeed, both the cytokines IL-4 and IL-5 as well as IL-13 were augmented in asthma mice, while the level of anti-inflammatory cytokines IL-2, IFN-ɣ, and IL-10 were drastically reduced." (PMID 36685604, 2022). "We noted that IL-10 was induced by RV but was not differentially induced in asthma, suggesting the anti-viral immunity is accompanied by the regulatory cytokine IL-10 in both healthy and asthmatic subjects." (PMID 36366542, 2022). "In conclusion, methane is a readily available and inexpensive molecule potentially suitable for human use, which can alleviate asthma-induced lung injury and EOS infiltration through the IL-10 pathway by increasing Tregs and decreasing NF-κB and p38 MAPK in a mouse model." (PMID 35812246, 2022). "At four weeks, later occurrence of AD, CMA, and asthma was positively correlated with calprotectin (r = 0.61), IL-1β (r = 0.58), EDN (r = 0.57), and TGF-β (r = 0.57), and negatively correlated with IL-6 (r = −0.71) and IL-10 (r = −0.61)." (PMID 35628877, 2022). "Besides, we found a positive correlation between BIRC3 and IL-10, IL-33, and TSLP in induced sputum of asthma (p < 0.05)." (PMID 35287655, 2022). "Interestingly, we found that most of the cytokines (IL-12p70, IL-13, IL-4, IL-6, TNF-α, and IL-8) in the asthma patients tend to increase when the low expression of eosinophils; but in the ACO group, only INF-γ and IL-10 showed an increase." (PMID 36311545, 2022). "Although the contribution of Tregs in asthma is not fully addressed, clinical improvement following allergen immunotherapy (AIT) for asthma suggested an association with the induction of IL-10-, IL-35- and TGF-β-producing Tregs and Foxp3+ Tregs." (PMID 35757774, 2022). "Furthermore, Treg cytokines (IL-10 and TGF-β, among others) were reduced in patients with asthma and animal models of asthma." (PMID 34526979, 2021).
asthma (continued). "The inhibition of RORγt also attenuated the effects of anti-miRNA-221-5p on the increased levels of IL-6, IL-17, IL-21 and IL-22 levels, and inhibited levels of IL-10, IL-35 and TGF-β in in vitro model of asthma following anti-miRNA-221-5p, in comparison with anti-miRNA-221-5p group." (PMID 34863307, 2021). "The inhibition of SOCS1 attenuated the effects of anti-miRNA-221-5p on the increased levels of IL-6, IL-17, IL-21 and IL-22, and suppressed levels of IL-10, IL-35 and TGF-β in in vitro model of asthma following anti-miRNA-221-5p, compared with anti-miRNA-221-5p group." (PMID 34863307, 2021). "The inhibition of FOXP3 attenuated the effects of miRNA-221-5p on the inhibition of IL-6, IL-17, IL-21 and IL-22 levels, and promotion of IL-10, IL-35 and TGF-β levels in in vitro model of asthma following anti-miRNA-221-5p, in comparison with anti-miRNA-221-5p group." (PMID 34863307, 2021). "However, studies in animal models of allergic airway inflammation have investigated a fair amount of preclinical and clinical research, which included the key roles of FOXP3+ Treg, IL-10, and TGF-β in asthma prevention." (PMID 33267824, 2020). "il-10, il-4, il-13, il-17a, il-2, tlr4, tlr9, ccl2, csf2, and vegfα are top 10 hub nodes in the PPI network, so we inquired the expression profiles of these genes in asthma from the GEO database." (PMID 33133221, 2020). "In addition, OBE treatment decreased the pro-asthma TNF-α but increased the Th2 anti-inflammatory cytokine, IL-10." (PMID 33123005, 2020). "However, higher levels of IL-4, IL-17, IL-6, and IL-10 mRNA and lower levels of IFN-γ and TGF-β mRNA were observed in lungs of mice from the asthma group relative to those from the normal or PBS group." (PMID 32549755, 2020). "One study revealed that under dexamethasone stimulation, CD4+ T cells from patients with steroid-resistant asthma failed to induce IL-10 synthesis." (PMID 32054098, 2020). "In asthma, SIT with allergens induces IL-10 producing B cells." (PMID 30818819, 2019). "Interleukin-10 (IL10) and interferon gamma (IFN-γ) are protective cytokines against asthma." (PMID 32641957, 2019). "Finally, further studies to investigate the mechanisms involving the influence of LMO2, IL10, and GSTM1 genes upon PTS and childhood asthma development are needed." (PMID 31214241, 2019). "In the present study, CCR7 knockdown increased the protein expression levels of IL-10 and TGF-β in allergy-induced asthma, suggesting that CCR7 may serve an important role in immune tolerance in allergy-induced asthma." (PMID 31545493, 2019). "However, it has been reported that people with asthma have decreased percentages of CD24+CD27+ B cells, which are required for the induction of IL10+ T cells." (PMID 29881878, 2018). "For TBXAS1 rs757760, MS4A2 rs502581, IL10 rs3024498, and ACE (rs4293 and rs4309), we did not detect any statistical association comparing AERD vs. asthma/HC or asthma vs. HC, in the allelic, recessive and codominant models (p > 0.05)." (PMID 30254660, 2018). "Similar findings were observed in PBMCs from patients with asthma, either infected or uninfected by S. mansoni, where the addition of Sm29 antigen led to an increase in the Treg response with IL-10 production and no increase in the Th2 response." (PMID 30687325, 2018). "The IL-4, IL-5 and IL-10 levels of allergic rhinitis, asthma and complication groups were significantly different from those of the control group (P<0.01) (Table-III).The IL-5 levels of allergic rhinitis and asthma groups were significantly different (P<0.01)." (PMID 30344593, 2018). "In addition to previously identified variables, the data provide further evidence for the importance of IL-2, IL-5, IL-6, IL-8, IL-10, IFN-γ, TNF, asthma, polyposis, and aspirin sensitivity, in efforts to demarcate distinct endotypes of CRS." (PMID 30283438, 2018).
asthma (continued). "Early studies showed that DC-derived IL-10 production is profoundly diminished in allergic rhinitis (AR) children regardless of the presence or absence of asthma, while DC-derived IL-12 secretion as well as T cell cytokine secretion were unchanged." (PMID 29616018, 2018). "While IL-10 showed up to 10-fold down-regulation in the group of severe asthma, its expression level was not correlated with severity of asthma." (PMID 30915130, 2018). "Comparatively similar levels were recorded for nine out of the 10 cytokines measured [e.g., – Interleukin (IL)-1β, IL-6, IL-10], regardless of study participant asthma status." (PMID 28424616, 2017). "However, the levels of serum IFN-γ, IL-4, and IL-17A levels were increased while the levels of IL-10 were increased by C5aRA treatment in RSV-infected, asthma and RSV-infected asthma mice." (PMID 29123203, 2017). "Agents targeting other asthma-related pathways and factors, such as Th17 and immunosuppressive cytokines (IL-10 and TGF-β), were not evaluated in this study." (PMID 28729731, 2017). "Again, intake of active vitD3 by asthma patients led to an increased expression of TLR9 but not other TLRs by IL-10 secreting CD4+ T cells." (PMID 27506771, 2016). "CR‐specific IL‐10 and IL‐13 responses were increased in CR‐sensitive subjects, with or without asthma, whereas asthma alone did not result in increased responses compared to participants without asthma or CR sensitivity." (PMID 27042305, 2016). "Takanashi with his team observed a significant reduction in IL-10 levels and a small number of IL-10-expressing cells in the sputum of patients with asthma and COPD and healthy smokers compared with nonsmokers." (PMID 27891067, 2016). "The Th2 cytokines (IL-5) and regulatory T cytokine (Treg, IL-10) were also elevated in patients with asthma and allergic rhinitis but not atopic dermatitis in this study." (PMID 27918476, 2016). "We investigated whether a statin improves the IL-17/IL-10 imbalance in patients with COPD, as has previously been demonstrated in patients with asthma." (PMID 26043025, 2015). "In sera, the levels of IgE and IL-4 were significantly higher in asthma mice than in control mice; the levels of IFN-γ were significantly lower in all treatment groups than in control mice; and the levels of IL-10 were significantly higher in the OVA+rAdV-CTLA4Ig DCs mice than in the other groups." (PMID 25860995, 2015). "In contrast, the CA heterozygous IL10-571C>A genotype was increased in patients with asthma and Ole e 2 sensitization compared with Ole e 2 nonsensitized patients with asthma (45.7% versus 21.4%, P = 0.02, OR, 3.08; 95% CI, 1.13–8.4)." (PMID 25759826, 2014). "CA heterozygous IL10-571C>A genotype was increased in patients with asthma and Ole e 2 sensitization compared with Ole e 2 nonsensitized patients with asthma (45.7% versus 21.4%, P = 0.02, OR, 3.08; 95% CI, 1.13–8.4)." (PMID 25759826, 2014). "In some B cell transfer studies involving cells isolated from helminth infected mice, there were also notable suppressive effects on asthma that were independent of IL-10, but the mechanisms were not determined." (PMID 23429492, 2013). "Although evidence for a role of M2-like macrophages in asthma is scarce, these findings suggest a protective effect since active IL-10 production by these cells is low in moderate asthma and absent in severe asthma." (PMID 23533311, 2013). "It was reported that this intermediate CD14+CD16+ subset (same subset is also referred to as CD14++CD16+ or CD14highCD16+) was expanded in patients with allergies and asthma and expressed a number of M2 surface markers such as CD163, CX3CR1, IL-4R, TGF-β1 and IL-10." (PMID 24358127, 2013). "In addition, these DCs induced the differentiation of IL-10- and IFN-γ-secreting T cells, and adoptive transfer of OVA-pulsed Dll4-pretreated DCs alleviated OVA-induced asthma in recipient mice." (PMID 23696838, 2013).
asthma (continued). "M2-like macrophages seem to be beneficial to the resolution of asthma through production of IL-10 but are not present or not functional in asthma, and therefore allergic inflammation can progress." (PMID 23533311, 2013). "Regulatory T cells from patients with severe therapy-resistant asthma do not have an increase in IL-10 following corticosteroid exposure." (PMID 23896653, 2013). "Since pDCs exposed to NP switched their cytokine pattern from type I IFNs and IL-10 to TNF-α, it suggested that NP exposure might enhance the allergic responses of diseases such as asthma." (PMID 24039973, 2013). "The present study demonstrates that BUD, an inhaled corticosteroid widely used for the management of bronchial asthma, controls asthma inflammation modulating ICOS, cell survival, Foxp3 and IL-10 expression differently in CD4+/CD25− and in CD4+/CD25+ cells in peripheral blood." (PMID 23251336, 2012). "Statins restore corticosteroid sensitivity in patients with asthma, possibly by restoring HDAC activity or by increased induction of indoleamine 2, 3-dioxygense resulting in increased secretion of the anti-inflammatory cytokine IL-10." (PMID 21473764, 2011). "Unexpectedly, we also showed a weak correlation between IL-10 producing CD4+ T cells and the severity of asthma which may suggest that the expression of this cytokine is associated with aggravated allergic inflammation." (PMID 21197090, 2010). "Surprisingly, none of the promoter polymorphisms in IL10 were associated with asthma or atopy in the SAGE and CAPPS populations with the exception of rs1800896, which was associated with asthma in CAPPS." (PMID 19852851, 2009). "None of the well-defined asthma/inflammatory genes (Il1b, Il4, Il10, Il13, Il6, Tnfa, Infg, Tgfb1) are differentially expressed, although they connect many of the genes that are." (PMID 18087596, 2007). "Asthmatic mice with and without fluconazole exhibited retardation of weight gain, increased IgE and IL-4 in serum, increased serum IL-6 but not serum TNF-α (increased serum IL-10 only in asthma with fluconazole), and prominent IL-4 and IgE in the lung homogenates." (PMID 39484217, 2024). "Hence, in our mouse model of asthma, major indicators relating to the asthma model (e.g., airway hypersensitivity, total serum IgE, IFN-γ, IL-4, IL-10, IL-13, and inflammatory cell count in BALF) were detected to evaluate the physiological and biochemical changes induced by the antigen (OVA)." (PMID 38674852, 2024). "In addition, histamine is found to promote IL‐10 and inhibit TGF‐α in OVA‐induced asthma in mice, thereby reducing the total number of cells in bronchoalveolar lavage fluid (BALF) and the number of inflammatory factors such as IL‐4, IL‐5, and IL‐13 in lung tissue." (PMID 38687096, 2024). "Children with asthma had higher levels of IL-2 (p = 0.005), IL-5 (p < 0.001), IL-13 (p = 0.021), IL-17A (p < 0.001), IL-22 (p < 0.001), IL-33 (p < 0.001), TNF-α (p < 0.001), and lower levels of IL-10 (p = 0.046) and leptin (p < 0.001) compared to those without asthma." (PMID 39902293, 2024). "Similarly, IL-10 showed consistent decrease in asthma only, and obesity only groups, however, no further significant decrease was observed in children with concurrent obesity and asthma." (PMID 39902293, 2024). "Endotype, sex, age, asthma history, LM score, GOS score, sinus dominance, olfactory CT score, tissue eosinophilia, HNE subepithelial count, HNE perivascular count, serum eosinophil, IL5, IL6, INFγ, TNFɑ, and IL10 saw significant differences between the two groups." (PMID 36428479, 2022). "Our experimental results indicated that MS ameliorated asthma-induced AHR and decreased cellular infiltration in the lung epithelium, decreased EOS cell counts in BALF and the lungs, lowered proinflammatory CK (IgE, IL-4, and IL-5), and augmented anti-inflammatory CK (IL-10) expression." (PMID 35812246, 2022).